CXXC5 (CXXC finger protein 5)
Diseases named in the same sentence as CXXC5 in open-access papers (continued):
Sharing a sentence is not in itself a finding about the gene and the disease.
tumor (continued). "As expected, the same methylation pattern of PFKFB2, CXXC5 (tumor hypomethylation in relation to NT and BTL), and ATPV6V0C (tumor hypermethylation in comparison with NT and BTL) described in the microarray analysis and in the TCGA cross-study validation was confirmed." (PMID 30884810, 2019). "Since CXXC5 regulates immune response, angiogenesis, and fibroblast differentiation, it is not difficult to speculate that CXXC5 may play an essential role in the tumor microenvironment that promotes or inhibits carcinogenesis." (PMID 39806388, 2025). "In addition, CXXC5 expression was positively correlated with infiltration of CD8+ T cells, resting memory CD4+ T cells, resting NK cells, activated dendritic cells, and memory B cells, suggesting that CXXC5 may be involved in CML anti-tumor immunity." (PMID 38283355, 2023). "No similarity was seen with the recently described HGNET_MN1 tumor type, which is characterized by MN1:BEND2 and MN1:CXXC5 (but not PATZ1) fusions." (PMID 34417833, 2021).
cancer (13 papers, 2012 to 2025). A tumor composed of atypical neoplastic, often pleomorphic cells that invade other tissues. "Abnormalities in the expression or function of CXXC5 are linked to pathological conditions such as cancer development, restricted hair regeneration, and abnormal fibrosis." (PMID 39806388, 2025). "CXXC5 regulates physiological processes such as angiogenesis, hair regeneration, and growth and development, and its aberrant expression or function is linked to various diseases, including cancer." (PMID 39806388, 2025). "However, the molecular mechanism underlying the relationship among CXXC5, immunotherapy, and vitamin supplementation in cancer patients remains to be further elucidated." (PMID 36539038, 2023). "Besides, CXXC5 overexpression was associated with the poor prognosis of malignant tumors." (PMID 32337277, 2020). "The complex signaling pathways and target genes associated with CXXC5 have different regulatory effects on tumors, which has resulted in the intricate and multifaceted role of CXXC5 in regulating tumorigenesis and cancer progression." (PMID 39806388, 2025). "Currently, the regulatory role of CXXC5 in cancer development focuses on the effects of CXXC5 on cancer cell proliferation, invasion, resistance to apoptosis, and others." (PMID 39806388, 2025). "Regardless of the strategy, it is necessary to consider the dual role of CXXC5 in cancer progression when targeting it for therapeutic purposes." (PMID 39806388, 2025). "Previous studies have shown that CXXC5 promote apoptosis in neurons and cancer cells by amplifying the TGF-β-SMAD pathway." (PMID 34621736, 2021). "Furthermore, CXXC5 even displays "opposite" regulatory functions at different stages of the same cancer type's development." (PMID 39806388, 2025). "Activation of this inhibitory potential in some cancers where CXXC5 acts as an oncogene with high expression may restrain cancer development more efficiently." (PMID 39806388, 2025). "The additional regulatory roles of CXXC5 on cancer development deserve further investigation." (PMID 39806388, 2025). "Furthermore, we describe the role of CXXC5 in various physiological and pathological processes, in particular, its role in the development of cancer." (PMID 39806388, 2025). "Overall, KY19382 and KY19334 could be used as agents to treat cSCC and other types of cancer caused by CDK1 overexpression, as well as diseases caused by cytoplasmic accumulation of CXXC5." (PMID 40887499, 2025). "Given that aberrant CXXC5 expression is involved in various human diseases, especially cancer, it is reasonable to believe that targeting CXXC5 could be an effective clinical approach to treat these diseases." (PMID 30479059, 2019). "However, from the point of view regarding CXXC5-regulated physiological processes, CXXC5 may have a more multidimensional impact on cancer development." (PMID 39806388, 2025). "The indirect activation of the Wnt/β‐catenin signaling via release of the negative feedback loop in CXXC5−/− mice may cause less risk of cancer occurrence, compared with the direct activation of the pathway." (PMID 26941261, 2016). "Overall, the bone anabolic therapy activating the Wnt/β‐catenin signaling via inhibition of Dvl–CXXC5 interaction may not cause any critical problem related to cancer." (PMID 26941261, 2016). "It contains the protocadherin gene cluster, PCDHA, B and G and genes involved in cancer such as EGR1, CTNN1A, JMJD1B, and CXXC5." (PMID 23293768, 2012). "One early study demonstrated that CXXC5, an essential effector in the treatment of APL with all-trans retinoic acid, could promote terminal differentiation of cancer cells." (PMID 39806388, 2025). "In addition, gain of function of CXXC5 induced inhibition of target genes, such as TSC1, and regulated the mTOR pathway positively, which could regulate the expression of PD-L1 in cancer cells." (PMID 36539038, 2023). "We also did not observe any sign for cancer development in CXXC5−/− mice, grown up to 1.5 years." (PMID 26941261, 2016).
infection (4 papers, 2007 to 2025). The state of being infected such as from the introduction of a foreign agent such as serum, vaccine, antigenic substance or organism. "The expression of CXXC5 is downregulated in muscle tissues in COVID-19 induced cytokine storms and correlates with infection-induced muscle loss." (PMID 39806388, 2025). "Differential gene expression analysis showed that increased amounts of Tfh2 are specifically enriched for Cxxc5 and Spock2 after infection." (PMID 37039643, 2023). "The optimal infection efficiency (100 MOI) of Ad-CXXC5, Ad-GFP, and Ad-shRNA-CXXC5 adenoviruses was screened, and the stable strain of MLFs was constructed." (PMID 32337277, 2020).
metabolic disease (2 papers, 2022 to 2023). A congenital disorder (due to inherited enzyme abnormality) or acquired (due to failure of a metabolically important organ) disorder resulting from an abnormal metabolic process. "Cytosolic CXXC5 accumulation has been observed in several diseases, such as osteoporosis, alopecia, and metabolic diseases, and is accompanied by impaired regeneration of damaged tissues." (PMID 37524876, 2023). "Overall, inhibition of CXXC5 function by small molecule‐mediated interference Dvl binding is a potential therapeutic approach for the treatment of metabolic diseases." (PMID 35384342, 2022). "HFD‐fed mice treated with KY19334, a small molecule inhibiting CXXC5‐Dvl protein–protein interaction (PPI), was used to assess the role of CXXC5 in metabolic diseases." (PMID 35384342, 2022). "The clinical implications of the functional roles of CXXC5 in metabolic diseases and their relationship with Wnt/β‐catenin signalling were investigated in human adipose tissues." (PMID 35384342, 2022). "The therapeutic effects of KY19334 on metabolic diseases phenotypes were acquired by restoration of suppressed Wnt/β‐catenin pathway via blockade of the functions of the aberrantly overexpressed Cxxc5." (PMID 35384342, 2022). "The functional role of CXXC5 as a driving factor in metabolic diseases was indicated by the induction of Cxxc5 in adipose and liver tissues of HFD‐fed obese mice." (PMID 35384342, 2022). "Blockade of the CXXC5‐Dvl PPI as a strategy for the treatment of metabolic diseases was further supported by the similar physiological improvement of metabolic abnormalities in both Cxxc5−/− mice and KY19334‐treated Cxxc5+/+ mice fed an HFD." (PMID 35384342, 2022). "Moreover, the significance of CXXC5 as a target for metabolic diseases was indicated by the absence of phenotypes of metabolic abnormalities resulting from Cxxc5 loss." (PMID 35384342, 2022).
hematopoietic system tumors (1 paper, 2025). "CXXC5 is intimately associated with the development of hematopoietic tumors." (PMID 39806388, 2025). "Multiple factors play a role in the regulation of the expression or function of CXXC5 in hematopoietic tumors." (PMID 39806388, 2025). "Further data are required to elucidate whether methylation is involved in the regulation of CXXC5 in hematopoietic tumors." (PMID 39806388, 2025).
CXXC5 also shares sentences with these, for which no sentence is quoted: breast tumor (4 papers); prostate carcinoma (3); acute lymphoblastic leukemia (2); cardiovascular disease (2); liver cancer (2); malignant peripheral nerve sheath tumor (2); adenocarcinoma (1); angina (1); astrocytoma (1); Calcium nephrolithiasis (1); dysplasia (1); endometrial carcinoma (1); fibrosis (1); gastrointestinal infections (1); glioblastoma multiforme (1); ischemia (1); ischemic heart disease (1); malignant melanoma (1); metastatic malignant melanomas (1); myocardial infarction (1); nervous system tumors (1); neuroepithelial tumor (1); non-alcoholic steatohepatitis (1); papillary thyroid cancer (1); pneumonia (1); prostate adenocarcinoma (1); Recurrent otitis media (1); sarcoma (1); sinusitis (1); Stroke (1).
A further 2 diseases each share a sentence with CXXC5 in 1 paper.